OR2AP1 (olfactory receptor family 2 subfamily AP member 1)
Description:
Odorant receptor.
Synonyms: OR2AP1P
Tractability: Antibody: UniProt places it where antibodies can reach, with medium confidence; UniProt predicts a signal peptide or a membrane-spanning region; its Gene Ontology location is reachable by antibodies, with medium confidence.
Gene: Protein-coding gene on chromosome 12 (55,572,468 to 55,575,612, forward strand). Ensembl gene ENSG00000179615.
Subcellular location: Cell membrane
Pathways (Reactome):
Sensory Perception: Expression and translocation of olfactory receptors
Gene Ontology:
Molecular function: olfactory receptor activity; G protein-coupled receptor activity
Biological process: detection of chemical stimulus involved in sensory perception of smell; G protein-coupled receptor signaling pathway
Cellular component: plasma membrane; membrane
Genetic constraint (gnomAD): Loss-of-function variants: 20 observed, 10.99 expected, observed/expected ratio (o/e) 1.82, 90% interval 1.21 to 1.97. The synonymous counts are far from expectation, so gnomAD's model fits this gene poorly and the ratio says little. Missense variants: 449 observed, 317.21 expected, observed/expected ratio (o/e) 1.42, 90% interval 1.31 to 1.53. Synonymous variants: 157 observed, 117.58 expected, observed/expected ratio (o/e) 1.34, 90% interval 1.17 to 1.52.
Homologues: Orthologues: chimpanzee OR2AP1 (98% identical), macaque OR2AP1 (95% identical), mouse Or6c8 (90% identical), rat OR6c8 (89% identical), mouse Or6c8b (87% identical). Paralogues in human: OR6C4 (80% identical), OR6C76 (67% identical), OR6C74 (65% identical), OR6C3 (64% identical), OR6C6 (64% identical), OR6C75 (64% identical), OR6C70 (63% identical), OR6C2 (62% identical), OR6C65 (61% identical), OR6C1 (61% identical), OR6C68 (59% identical), OR6J1 (46% identical), and 6 more.